CXCL3 (C-X-C motif chemokine ligand 3)
Description:
Ligand for CXCR2 (By similarity). Has chemotactic activity for neutrophils. May play a role in inflammation and exert its effects on endothelial cells in an autocrine fashion. In vitro, the processed form GRO-gamma(5-73) shows a fivefold higher chemotactic activity for neutrophilic granulocytes.
Synonyms: GRO3; GROG; SCYB3; MIP-2b; CINC-2b; MIP2B
Tractability: Antibody: its Gene Ontology location is reachable by antibodies, with high confidence; UniProt places it where antibodies can reach, with medium confidence; UniProt predicts a signal peptide or a membrane-spanning region.
Gene: Protein-coding gene on chromosome 4 (74,036,589 to 74,038,807, reverse strand). Ensembl gene ENSG00000163734.
Subcellular location: Secreted
Pathways (Reactome):
Signal Transduction: Chemokine receptors bind chemokines; G alpha (i) signalling events
Gene Ontology:
Molecular function: chemokine activity
Biological process: neutrophil chemotaxis; chemotaxis; defense response; immune response
Cellular component: extracellular region
Genetic constraint (gnomAD): Loss-of-function variants: 10 observed, 12.24 expected, observed/expected ratio (o/e) 0.82, 90% interval 0.5 to 1.38. The upper end of that interval is the gene's LOEUF score, 1.38, which puts it in group 5 of 6, group 1 being the genes least tolerant of losing a copy. Missense variants: 149 observed, 123.41 expected, observed/expected ratio (o/e) 1.21, 90% interval 1.06 to 1.38. Synonymous variants: 61 observed, 52.34 expected, observed/expected ratio (o/e) 1.17, 90% interval 0.95 to 1.44.
Homologues: Orthologues: chimpanzee CXCL3 (96% identical), pig CXCL2 (68% identical), macaque CXCL3 (66% identical), mouse Cxcl2 (58% identical), rat Cxcl1 (55% identical), rat Cxcl2 (53% identical), mouse Cxcl1 (52% identical), mouse Cxcl3 (50% identical), rat Cxcl3 (50% identical), guinea pig Cxcl2 (49% identical). Paralogues in human: CXCL2 (88% identical), CXCL1 (87% identical), PPBP (45% identical), CXCL5 (43% identical), CXCL6 (39% identical), CXCL8 (37% identical), CXCL9 (36% identical), PF4 (33% identical), PF4V1 (30% identical), CXCL11 (25% identical), CXCL13 (24% identical), CXCL10 (20% identical).
Diseases named in the same sentence as CXCL3 in open-access papers:
CXCL3 is named in the same sentence as 157 diseases in open-access papers, as found by Europe PMC text mining. Sharing a sentence is not in itself a finding about the gene and the disease. The quoted sentences say what the papers report.
breast cancer (28 papers, 2014 to 2025). A primary or metastatic malignant neoplasm involving the breast. "Our findings indicated that high CXCL2/9/10/12/13 expression and low CXCL3 expression were associated with favorable OS in breast cancer patients." (PMID 32963527, 2020). "We examined S100A8, IL-6, IL-6R, IL-8, and CXCL3 genes; each of these are known to be differentially expressed in breast cancer and are being evaluated as biomarkers and therapeutic targets." (PMID 39199680, 2024). "In this way, the expression of CXCL2/growth-regulated oncogene-β (GRO-β) and CXCL3/growth-regulated oncogene-γ (GRO-γ) also increases in breast cancer cells." (PMID 37108425, 2023). "Although CXCL3 did not specifically recruit MHCIIhi neutrophils to the lungs, blocking CXCL3 to suppress lung metastasis of breast cancer is an interesting and valuable topic worthy of further verification." (PMID 37563136, 2023). "Previous studies have suggested that CXCL3 can enhance the proliferation and migration of prostate cancer, breast cancer, and colorectal cancer." (PMID 36290882, 2022). "The Kaplan–Meier curves showed that in breast cancer patients, higher expression of mRNAs of CXCL2, 6, 9, 10, 12, 13, 14 and lower expression of mRNAs of CXCL3, 8, and 17 was significantly associated with longer overall survival (OS) (p < 0.05)." (PMID 34439306, 2021). "Many studies showed that CXCL3 is highly expressed in many different types of cancers, including breast cancer, prostate cancer, cervical cancer, and ovarian cancer, and its up-regulated expression is closely related to clinical characteristics." (PMID 34870709, 2021). "Taken together, CXCL3 and its signaling is a potential target for preventing metastatic breast cancer." (PMID 32986377, 2020). "Among them, breast cancer patients with high transcriptional levels of CXCL2/9/10/12/13 and low transcriptional level of CXCL3 were associated with a better prognosis." (PMID 32963527, 2020). "CXCL3 is related to the occurrence and development of prostate cancer, colon cancer, and breast cancer." (PMID 32600423, 2020). "Leading-edge analysis (for genes that contributed most to enrichment in pathways) showed genes that are upregulated downstream of KRAS in lung or breast cancer (e.g., CXCL3, ADAM8, and L.I.F.)." (PMID 32455851, 2020). "In the context of breast cancer, chemokines have been implicated in promoting the malignant phenotype: CXCL3, CXCL12, CXCL13, CCL21 and CCL5 are associated with tumour progression and metastasis in breast cancer." (PMID 27335323, 2016). "Although a few studies have reported the role of CXCL3 in breast cancer lung metastasis, our study confirmed that the blockade of CXCL3 could suppress the metastasis of breast cancer to the lung in vivo." (PMID 37563136, 2023). "It was demonstrated that CXCL3 is closely related to tumor metastasis of breast cancer." (PMID 34870709, 2021). "CXCL3 promoted breast cancer cell proliferation through the JAK2/STAT3 signaling pathway." (PMID 34870709, 2021). "However, the effect of brazilin on CXCL3 signaling related to TNFα in metastatic breast cancer remains elusive." (PMID 32986377, 2020). "CXCL3, a well-known oncogene, has been confirmed to promote pathological progression in various malignancies, such as colorectal cancer (CC), prostate cancer, breast cancer and neuroblastoma tumors." (PMID 32614785, 2020). "On the one hand, CXCL3 had a significant developing gene in colon carcinoma and a significantly down-regulated expression level in both lymph node metastasis and distant metastasis, and high expression of CXCL3 in breast cancer cells was relevant with tumor metastasis." (PMID 25485631, 2014). "Neutrophil infiltration had a direct relationship with the expression of IL1R1, IL1RN, IL1RAP, IL6ST, CXCL3, CXCL5, and CXCL6 in most of the subtypes of the breast cancer patients analyzed." (PMID 39201290, 2024).
breast cancer (continued). "This article summarizes existing knowledge about the roles of CXCL ELR-positive chemokines CXCL1, CXCL2, CXCL3, CXCL5, CXCL6, CXCL7, and CXCL8 as peripheral blood and tissue markers in the diagnosis and prognosis of women with breast cancer." (PMID 37370728, 2023). "Our RNA-seq results showed that the expression of CXCL1, CXCL2, CXCL3, and CXCL8 was significantly increased in breast cancer cells after co-culturing with adipocytes." (PMID 35280694, 2022). "In breast cancer, the groups with higher expression of mRNAs of CXCL2, 6, 9, 10, 12, 13, and 14 and the groups with lower expression of CXCL3, 8, and 17 had significantly better overall survival (OS)." (PMID 34439306, 2021). "In another model of murine breast cancer, MMTV−Neu (Mouse Mammary Tumor Virus—Neu oncogene), we observed an increase of Cxcl1, Cxcl2, Cxcl3, and Cxcl5 levels in the tumor of MMTV−Neu animals compared to the mammary gland of WT animals." (PMID 34070438, 2021). "Here, we targeted CXCR2 for intervention in mice with mammary tumors, disrupting signals from its cognate ligands, CXCL1 and CXCL3." (PMID 33123173, 2020). "The results indicated that the expression levels of CXCL9, CXCL10, CXCL11, and CXCL13 were marked higher in breast cancer tissues than in normal tissues, while the expression levels of CXCL1, CXCL2, CXCL3, and CXCL12 were lower inversely." (PMID 32963527, 2020). "In breast cancer, CSF2 could activate the Stat3 pathway in CAA via paracrine or autocrine mechanisms, leading to increased expression and secretion of CXCL3." (PMID 39497824, 2024). "CXCL3 binds to CXCR2, a receptor on breast cancer cells, and activates FAK, which promotes a mesenchymal phenotype, invasion, and metastasis of breast cancer cells F12 expression might affect the OS of PTC patients by regulating metabolic pathways." (PMID 39497824, 2024). "Collectively, these data strongly indicate that CCL2, rather than CXCL3, recruits MHCIIhi neutrophils to promote lung metastasis of breast cancer." (PMID 37563136, 2023). "The results showed that α-CXCL3 could significantly inhibit the level of LIF mRNA in CAAs induced by breast cancer cells, and the ELISA results showed that the secretion of LIF in CAAs was inhibited by α-CXCL3." (PMID 35280694, 2022). "Therefore, we believe that breast cancer cells express more CXCL1, CXCL2, CXCL3, and CXCL8 after co-culturing with adipocytes." (PMID 35280694, 2022). "Additionally, high levels of CXCL1, CXCL3, CXCL5, CXCL6, CXCL7 and CXCL8 are observed in drug-resistant breast cancer cells, which diminishes the effectiveness of other medical interventions." (PMID 31788042, 2019). "Additionally, many markers we observed that defined our monocyte clusters (FABP5, FN1, IL1RN, CCL3, CCL4, CXCL8, CXCL3, IL1B) during transient, short-term CM stimulation, were elevated in either PD-L1pos or PD-L1neg TAMs isolated and sequenced from breast cancer." (PMID 40176808, 2025). "However, IL1RN, IL6ST, CXCL3, CXCL5, and CXCL6 gene expression levels were non-significant concerning clinical survival of breast cancer patients." (PMID 39201290, 2024). "However, IL1RN, IL6ST, CXCL3, CXCL5, and CXCL6 gene expression levels were non-significant concerning clinical survival of breast cancer patients according to the Cox proportional Hazard model." (PMID 39201290, 2024).
colorectal cancer (23 papers, 2019 to 2025). A primary or metastatic malignant neoplasm that affects the colon or rectum. "Results from another study on colorectal cancer (CRC) demonstrated that plasma CXCL3 levels are associated with tumor progression and poor prognosis in CRC patients." (PMID 41445742, 2025). "Herein, we investigated the association of the CXC-chemokine ligand 3 (CXCL3) with tumor progression and an unfavorable prognosis for colorectal cancer (CRC)." (PMID 35664357, 2022). "Analogously, in KRAS-mutated colorectal cancer, where ICI is ineffective, expression of key chemokines involved in IFN network signaling, such as CXCL3, are downregulated when KRAS is mutated due to direct interaction with IRF239." (PMID 40442146, 2025). "Studies have found that interferon regulatory factor 2 (IRF2) can improve colorectal cancer responsiveness to PD-1 therapy by directly inhibiting chemokine 3 (CXCL3)." (PMID 35923703, 2022). "There are investigations showing that CXCL3 is associated with vascular invasion and tumor capsule formation in HCC and is targeted by IRF2 to suppress MDSC migration and infiltration in colorectal cancer." (PMID 33552958, 2020). "Qi demonstrated that IRF-2 is a transcription factor of CENP-N that promotes CENP-N expression and activates the AKT cascade in nasopharyngeal cancer, while Liao proved that IRF-2 binds to the DNA promoter region of CXCL3 and blocks its transcription in colorectal cancer." (PMID 35115027, 2022). "KRAS-mediated repression of interferon regulatory factor 2 (IRF2) results in high expression of CXCL3, which binds to CXCR2 on myeloid-derived suppressor cells (MDSCs) and regulates the immune responses in colorectal cancers." (PMID 40547026, 2025). "For example, in colorectal cancer tissue, CXCL1, CXCL2, CXCL3, CXCL5, CXCL8, and CXCL11 were highly expressed, while CXCL12, CXCL13, and CXCL14 were little expressed." (PMID 36612163, 2022). "In colorectal cancer, KRAS activation is known to induce CXCL3 expression and the induction of MDSCs with CXCR2, the receptor of CXCL3." (PMID 34359568, 2021). "In KRAS-mutant colorectal cancer (CRC), KRAS∗-mediated repression of interferon regulatory factor 2 (IRF2) that directly represses CXCL3 expression results in high expression of CXCL3, which binds to CXCR2 on MDSCs and promotes their migration to the TME." (PMID 35003065, 2021). "Therefore, the CXC family plays an important role in the development of colorectal cancer, especially CXCL8, CXCL3, and CXCL1." (PMID 32462020, 2020). "The OS analysis of 10 core genes was performed by using the GEPIA tool website, and the results show that low expressions of AQP8, ZG16, CXCL3, and CXCL8 may predict poor survival outcome in colorectal cancer." (PMID 32462020, 2020). "The results of OS analysis have shown that low expressions of AQP8, ZG16, CXCL3, and CXCL8 may predict poor survival outcome in colorectal cancer." (PMID 32462020, 2020). "Gene Expression Profiling Interactive Analysis (GEPIA) overall survival (OS) has shown that low expressions of AQP8, ZG16, CXCL3, and CXCL8 may predict poor survival outcome in colorectal cancer." (PMID 32462020, 2020). "Gene Expression Profiling Interactive Analysis (GEPIA) overall survival (OS) analysis has shown that low expressions of AQP8, ZG16, CXCL3, and CXCL8 may predict poor survival outcome in colorectal cancer." (PMID 32462020, 2020). "Oncogenic activation of KRAS in colorectal cancer cells, depressed the expression of IRF2 with a capacity to depress CXCL3 expression and eventually enhanced expression of CXCL3 which promoted intratumoral migration of PMN–MDSCs expressing CXCR2, a receptor for CXCL3." (PMID 32422991, 2020). "In colorectal cancer models KRASG12D has shown to downregulate the expression of interferon regulatory factor 2 (IRF2), which in turn suppresses CXCL3 expression, resulting in high expression of CXCL3 and promoting migration of myeloid-derived suppressor cells to the tumor microenvironment." (PMID 33777798, 2021).
colorectal cancer (continued). "In addition, it was described that KRASG12D could promote Treg transformation by blocking the interferon regulatory factor 2 (IRF2), resulting in repression of IRF2/CXCL3 pathway and binding of CXCL3 to CXCR2 on MDSCs, driving immune suppression and immune therapy resistance in colorectal cancer." (PMID 35159208, 2022).
colon carcinoma (20 papers, 2014 to 2025). "Our previous study also demonstrated a direct association between CXCL3 upregulation and improved diagnostic accuracy in colon cancer." (PMID 41259383, 2025). "Survival analysis conducted on GEO cohorts and Guangxi Medical University revealed that the high CXCL3 expression levels were associated with a shorter OS in colon cancer patients." (PMID 34233297, 2021). "Chen and colleagues found that CXCL1, CXCL2, and CXCL3 were all highly expressed in colon cancer tissues." (PMID 34269159, 2021). "There are also reports in the literature that the effect of suppressing the development of colon cancer can be achieved by immunosuppression of CXCL3." (PMID 32600423, 2020). "Previous reports identified an upregulation in the expression of CXCL2 and CXCL3, promoting cancer stem cell like properties and tumorigenesis in LoVo colon cancer cells in culture." (PMID 31835892, 2019). "PTGS2, also called COX-2, has been reported to play a critical role in tumor growth and metastasis in colon cancer and high expressions of CXCL2 and CXCL3 have been associated with tumor metastasis." (PMID 29215599, 2017). "Moreover, CXCL3 has been shown to be enriched in the plasma of colon cancer patients, with elevated levels correlating with aggressive clinical features such as advanced stage, poor differentiation, and lymph node metastasis." (PMID 41259383, 2025). "Moreover, the IL6/JAK/STAT3 pathway has been found to upregulate CXCL1, CXCL2, CXCL3, and CXCL11 in patients with colon cancer, which was associated with prognosis." (PMID 35468892, 2022). "CXCL3 was significantly expressed at high levels in 23 unique analyses in colon cancer." (PMID 34439306, 2021). "Our results showed that CXCL1, CXCL2, CXCL3, and CXCL11 were all upregulated in colon cancer compared with healthy tissues, and in the colon cancer group, a high level of CXCL1, CXCL2, CXCL3, and CXCL11 was correlated with better survival in TCGA or GEO." (PMID 32337262, 2020). "CXCL1, CXCL2, CXCL3, and CXCL11 were upregulated in patients with colon cancer and significantly correlated with prognosis." (PMID 32337262, 2020). "We also showed that these two chemokines but also CXCL3 and CXCL5 were more expressed in tumors of patients with colon cancer as compared to healthy tissue." (PMID 29983866, 2018). "Notwithstanding, expression of CXCL2, CXCL3 and CXCL8 is increased in colon cancer compared with normal colon tissue and CXCL2 and CXCL3 expression has been found to be already upregulated in premalignant adenomas." (PMID 30591657, 2018). "The selectin E gene (SELE) was predicted to be downstream regulated by NFκB via such chemokines (CCL8, CXCL2, CXCL3), while previous studies observed that it activates the PI3K/NFκB pathway in colon cancer." (PMID 27078000, 2016). "In addition to CCL2, CXCR2 ligands including CXCL1, CXCL2, CXCL3, and CXCL8 produced by CRC cells and neutrophils themselves were found to be responsible for recruitment of CXCR2+ neutrophils/PMN-MDSCs to colon tumors." (PMID 31681563, 2019).